HOTAIRM1 (HOXA transcript antisense RNA, myeloid-specific 1)
Diseases named in the same sentence as HOTAIRM1 in open-access papers (continued):
Sharing a sentence is not in itself a finding about the gene and the disease.
tumor (continued). "Secondly, when combined treatment with knockdown of HOTAIRM1 could inhibiting tumor growth and prolong survival of animals for only a short period of time." (PMID 37171645, 2023). "Mechanistically, HOTAIRM1 could impair the antitumor immune response by MDSCs and delay tumor progression though increasing the expression of HOXA1 in MDSCs, which promotes Arg1 secretion." (PMID 37637063, 2023). "They found higher levels of HOTAIRM1 on tumor cell lines compared with controls." (PMID 37047453, 2023). "The variance of HOTAIRM1 expression in different neoplasms could control cancer cellular biological activities, making HOTAIRM1 a popular molecule in tumor therapy." (PMID 37529170, 2023). "These synergistic changes supported that SPON2 in CAFs could be regulated by HOTAIRM1 from tumor cell exosomes." (PMID 36153414, 2022). "After overexpression of HOTAIRM1, the invasion and migration of tumor cells were significantly improved, but after transfection of miR-328-5p simulant, the effect of HOTAIRM1 was weakened, and The overexpression efficiency of HOTAIRM1 and miR-328-5p was also verified." (PMID 36153414, 2022). "In our study, HOTAIRM1 was identified as an upregulated lncRNA and was found to be closely associated with OSCC overall survival (OS), tumor stage, genomic instability, the tumor cell stemness, the tumor microenvironment (TME), and immune inflammation." (PMID 35087800, 2021). "In this research, HOTAIRM1 expression levels were correlated with the types of the immune cells, and we speculated that HOTAIRM1 might influence the tumor immune microenvironment and thus promote the progression of OSCC." (PMID 35087800, 2021). "In addition, we identified a correlation between HOTAIRM1 expression and tumor stage, indicating that more advanced OSCC stage was associated with the higher expression of HOTAIRM1." (PMID 35087800, 2021). "We analyzed the correlation between upregulated HOTAIRM1 expression and clinical data of OSCC patients, in which OS and tumor clinical stages were associated with HOTAIRM1 expression, indicating an unfavorable prognosis as well as the prognostic value of HOTAIRM1 in OSCC." (PMID 35087800, 2021). "Meanwhile, in vivo studies showed that SNAI2 could promote the tumor progression, and HOTAIRM1 knockdown reversed this results." (PMID 33323548, 2020). "In vivo results confirmed that HOTAIRM1 promotes tumor progression in GBM." (PMID 33323548, 2020). "However, it has been found that HOTAIRM1 is related to the elevated migration and invasion of tumor cells." (PMID 32664703, 2020). "Moreover, our in vivo experiments further showed tumor growth was effectively suppressed by HOTAIRM1 silencing." (PMID 30376874, 2018). "A mouse tumor xenograft model was established to examine the effects of HOTAIRM1 on HNT in vivo." (PMID 29905017, 2018). "After HOTAIRM1 silencing cell proliferation, apoptosis, migration, invasion and tumor growth in vivo were assessed, which implied HOTAIRM1 might exert oncogenic properties in GBM." (PMID 30376874, 2018). "In vivo experiments showed knockdown of HOTAIRM1 lessened the tumor growth." (PMID 30376874, 2018). "HOTAIRM1 has been reported to play a significant role in many types of tumor." (PMID 29905017, 2018). "HOTAIRM1 was confirmed as a tumor suppressor via sponging miR‐148a and promote the expression of DLGAP1, which could be regarded as an important target for the prevention and treatment of HNT." (PMID 29905017, 2018). "We then detected HOTAIRM1 expression in tumour tissues and matched normal tissues." (PMID 27307307, 2016). "Notably, silencing HOTAIRM1 significantly inhibited tumor growth." (PMID 38012763, 2023). "Moreover, we discovered that HOTAIRM1 knockdown and a combinatorial strategy using autophagy inhibitor therapy may reprogram the tumor microenvironment for effective treatment of lenvatinib-resistant HCC." (PMID 37171645, 2023). "Besides, we also knocked down HOTAIRM1 of tumor cells and co-cultured with CAFs." (PMID 36153414, 2022).
tumor (continued). "Taken together, HOTAIRM1 maybe function as a tumour suppressor gene in CRC." (PMID 27307307, 2016). "Through direct interactions with known tumor suppressing miRNAs (MALAT1, HOTAIRM1), miRNA sponging (NEAT1, UCA1), and competition with miRNAs for mRNA binding (UCA1), lncRNAs drive oncogenesis in ATC via these dynamic interactions." (PMID 38785786, 2024). "However, it is rather frustrated that in this orthotopic transplantation tumor model, combined treatment with knockdown of HOTAIRM1 plus autophagy inhibitor and lenvatinib could inhibiting tumor growth and prolong survival of animals for a short period of time." (PMID 37171645, 2023). "For instance, HOX transcript antisense intergenic RNA (HOTAIR) and HOXA Transcript Antisense RNA Myeloid-Specific 1 (HOTAIRM1), which are located in the HOXC and HOXA loci, respectively, are strongly expressed in GBM where they have pro-tumor functions." (PMID 35563134, 2022). "Further mechanistical studies suggested that HOTAIRM1 competitively bound miR-133b-3p to regulate the expression of TGF-β, thus producing obvious pro-tumor effect." (PMID 33816233, 2021). "For HOTAIRM1 overexpressed by ELECTS, the tumor volume and weight are significantly higher than the control group." (PMID 34600532, 2021). "HOTAIRM1 has been found to enhance the expression of HOXA1 in MDSCs, and the upregulation of HOXA1 can delay tumor progression and enhance anti-tumor immune response by restraining the immunosuppressive activity of MDSCs." (PMID 34692550, 2021). "LncRNA HOTAIRM1 (HOXA transcript antisense RNA, myeloid-specific 1), under-expressed in OvCa cells and tumor tissues, also belongs to suppressor lncRNA." (PMID 33238475, 2020). "Finally, it was confirmed that HOTAIRM1 could enhance the expression of HOXA1 in MDSCs and that high levels of HOXA1, the target gene of HOTAIRM1, could delay tumor progression and enhance the antitumor immune response by downregulating the immunosuppression of MDSCs." (PMID 29662483, 2018). "We next examined the HOTAIRM1 expression in 109 HNT patient samples and confirmed the downregulation of HOTAIRM1 in tumor tissues than that in adjacent tissues." (PMID 29905017, 2018). "Mice inoculated intracerebrally with LN-229 control or HOTAIRM1 knock-down cells were evaluated for orthotopic tumor growth and survival either with or without single irradiation with 12 Gy at day 15 post tumor cell transplantation." (PMID 34584066, 2021). "The specific mechanism may be that HOTAIRM1 can enhance the expression of HOXA1 in MDSCs and high levels of HOXA1 can delay tumor progression and enhance the antitumor immune response by downregulating the immunosuppression mediated by MDSCs." (PMID 32005273, 2020). "Not surprisingly, tumor progression from HOTAIRM1-downregulated pGBM1 cells was much slower than that of a control tumor raised from control cells." (PMID 33323548, 2020). "To determine which type of non-tumor cell contributes to the altered TME, we used gene set variation analysis (GSVA) to estimate the gene set of immune cells and evaluate the correlation between immune cell types and HOTAIRM1 expression." (PMID 31477638, 2019). "However, several issues in this investigation remain to be resolved, such as the exact regulatory mechanism of HOTAIRM1/HOXA1 in MDSC function and the factors that induce the downregulation of HOTAIRM1 in MDSCs under tumor conditions." (PMID 29662483, 2018). "In our study, the HOTAIRM1 expression was inversely proportional to stromal cell and immune cell content, suggesting that HOTAIRM1 may promote the proliferation of OSCC cells and improve tumor purity." (PMID 35087800, 2021). "HOTAIRM1 was upregulated in plasma but not in tumor tissue from NSCLC patients." (PMID 32033141, 2020). "We analyzed the association between HOTAIRM1 expression level with patient age, gender, tumor WHO clinical grade and found HOTAIRM1 expression level was related to tumor grade and was not related to age and gender." (PMID 30376874, 2018).
tumor (continued). "More interestingly, down‐regulation of HOTAIRM1 in CRC tissues might be an independent biomarker without relation to other clinical characteristics such as age, sex, tumour localization, tumour size and TNM stage." (PMID 27307307, 2016).
cancer (31 papers, 2014 to 2025). A tumor composed of atypical neoplastic, often pleomorphic cells that invade other tissues. "Initially identified for its crucial role in granulocytic differentiation within NB4 promyelocytic leukemia, HOTAIRM1 has emerged as a notable lncRNA associated with cancer." (PMID 37705098, 2023). "Here, we aim to investigate the molecular mechanisms underlying the anti-cancer activity of Da0324 by regulating the lncRNA HOTAIRM1." (PMID 35711826, 2022). "Here, we aimed to investigate the molecular mechanisms underlying the anti-cancer effect of Da0324 through regulation of HOTAIRM1." (PMID 35711826, 2022). "It’s a sign that HOTAIRM1 may be a cancer-associated lncRNA and influences the malignant progression of some cancers." (PMID 35087800, 2021). "The molecular mechanism of cancer caused by upregulation of HOTAIRM1 and PCA3 in ATC still remains unknown." (PMID 32760219, 2020). "RUNX1-IT1, MALAT1, H19, and HOTAIRM1 have been widely associated with cancer in recent years." (PMID 28389671, 2017). "For instance, HOX antisense intergenic RNA myeloid 1 (HOTAIRM1) is an lncRNA that plays an oncogenic role in various cancers promoting VM." (PMID 40277941, 2025). "Of these genes, we highlight the long non-coding RNA (lncRNA) HOTAIRM1, which has known roles in many cancers, including colorectal." (PMID 38680862, 2024). "Emerging evidence has reported that aberrant expression of lncRNA HOXA transcript antisense RNA myeloid-specific 1 (HOTAIRM1) is found in multiple human diseases, including cancers, sepsis, and progressive bone disorders." (PMID 37529170, 2023). "Recent evidence has shown that HOTAIRM1 plays an important role in treatment resistance in different cancers." (PMID 37171645, 2023). "It was recently reported that HOTAIRM1 elicited apoptosis as presented by increased Bax expression and decreased Bcl-2 expression in carcinomas." (PMID 37529170, 2023). "The reason why HOTAIRM1 acts as a promoter or suppressor in opposite ways in different cancer is still unclear." (PMID 35711826, 2022). "Previous studies have shown the association of HOTAIRM1, CRNDE, and TUG1 expression in the pathogenesis of various cancers, including ALL." (PMID 37303492, 2022). "HOTAIRM1 has been shown to be a salient cancer-related lncRNA abnormally expressed in various cancers and can regulate cancer progression by affecting cell proliferation, apoptosis, invasion, and migration." (PMID 35350655, 2022). "For instance, HOXB-AS1 (p < 0.001) showed the highest correlation with stromal scores across the different cancer types followed by HOTAIRM1 (p < 0.001), and HOXA-AS2 (p < 0.05)." (PMID 34805277, 2021). "Although little is known regarding the role of HOTAIRM1 in the brain, its role in regulating proliferation and differentiation has been extensively studied in cancer cells." (PMID 34298885, 2021). "Some scholars proposed that a succession of genomic alterations in neoplastic cells are crucial triggering factors for cancers, therefore, we further assessed the correlation between HOTAIRM1 expression patterns and tumorigenic characteristics." (PMID 35087800, 2021). "Similar to our in vitro results, the expression of HOTAIRM1 and HOXA1 were up-regulated in the recurred cancer patient group, supporting our conclusion that HOTAIRM1 and HOXA1 are prospective indicators for tamoxifen resistance." (PMID 32284737, 2020). "The expression level of HOTAIRM1 in 43 Head carcinoma tissues (55 in total) and 41 Neck carcinoma tissues (54 in total) was downregulated compared to the corresponding adjacent normal tissues." (PMID 29905017, 2018). "Recent studies have shown that the function of HOTAIRM1 is different in different types of cancer." (PMID 35711826, 2022). "HOTAIRM1 functions as an oncogene in multiple types of cancers." (PMID 34600532, 2021).
cancer (continued). "Among these lncRNAs and mRNAs, lncRNA HOXA transcript antisense RNA myeloid-specific 1 (HOTAIRM1) participates in the reprogramming of chromatin organization and proliferation and metastasis of cancer, which has been found to be highly expressed in a variety of tumors including GBM." (PMID 34899682, 2021). "Besides some well-known cancer-associated lncRNAs such as LINC01158, LINC00461, XIST, and HOTAIRM1, we also identified several potential GBM progression-associated lncRNAs like POLR2J4, WWTR1-AS1, and VIM-AS1." (PMID 33505440, 2020). "HOTAIRM1 is a previously documented lncRNA, functionally involved in multiple cancers." (PMID 31512358, 2019). "However, altered HOTAIRM1 expression has now been reported in lots of human cancers." (PMID 37171645, 2023). "Moreover, functional assays showed that knockdown of HOTAIRM1 could attenuate the inhibitory effect of Da0324 on GC cell proliferation in vitro, suggesting that Da0324 exerts its anti-cancer effect at least in part via upregulation of HOTAIRM1." (PMID 35711826, 2022). "Among them, HOTAIRM1 and HAGLR showed relatively higher expression levels in all the cancer types than the other HOXATs." (PMID 34805277, 2021). "Notably, both HOTAIRM1 and PCAT14 were confirmed as the critical regulators in cancer by multiple previous studies, but less is known about their regulatory roles during hESC development." (PMID 36907881, 2023). "Whether HOTAIRM1 has other biological functions in NSCLC and whether SPON2, as an important cancer-promoting ECM protein, has other regulatory pathways deserve further investigation, and it is now underway in our group." (PMID 36153414, 2022). "Further, we found that HOTAIRM1 was indeed highly expressed in cancer samples but not in normal samples, even in the paired-samples comparison." (PMID 35087800, 2021). "The results in OCs were consistent with other cancer studies, and new findings were made; for example, five lncRNAs (MIR31HG34, HOTAIRM1, MIR155HG, ITGB2-AS1, HCP5, and SH3PXD2A-AS134) were reported in other different cancers, which confirmed the reliability of our newfound biomarkers." (PMID 31462944, 2019). "First, we tested HOTAIRM1 expression levels in different head and neck tumor cells compared with normal human nasopharyngeal epithelial cells (NP69 cell) and found that HOTAIRM1 expression was the lowest in Fadu cells in four cancer cells." (PMID 29905017, 2018). "Moreover, the lncRNAs HOTAIRM1, PTENP1, and MALAT1 were found to be involved in the activation of autophagy and regulation of several physiological processes and malignant phenotype of cancer cells." (PMID 33850225, 2021). "As a biomarker combination could be more powerful than a single biomarker, we decided to evaluate, in the same EV samples, the expression of other lncRNAs whose expression in tissue impacted prognosis in other cancers studied by our group, including HOTTIP, HOTAIR, HOXA11, and HOTAIRM1." (PMID 32244977, 2020). "Interestingly, HOTAIRM1 and HOXA-AS2 showed positive correlation with the other 16 HOXATs, suggesting that they possibly exert a regulatory effect on all the other 16 HOXATs and may be critical factors in cancer development." (PMID 34805277, 2021). "HOTAIRM1 was previously shown to interact with polycomb repressive complexes 1 (PRC1) and 2 (PRC2), but was not reported to be involved in cancer." (PMID 25296969, 2014). "In this study, as examples, we found that lncRNAs, HCCL5, HOTAIRM1, LINC00364 and PCBP2-OT1, which have been reported to promote the growth of cancer cells using pcDNA3/3.1, could not play the same role when expressed by lentiviral vector pCDH." (PMID 34600532, 2021).
cardiovascular diseases (1 paper, 2024). "Aberrant endothelial cell proliferation is closely related to various cardiovascular diseases, including AS; however, whether lncRNA HOTAIRM1 is also involved in this process remains unclear." (PMID 37898994, 2024).
hematological disorders (1 paper, 2023). "Eight of these lncRNAs have already demonstrated an involvement in hematological disorders: HOTAIRM1 gene is adjacent and antisense to the transcription start site of HOXA1, and its transcription is initiated from the shared promoter segment embedded in a CpG island between the two genes." (PMID 37486375, 2023).
HOTAIRM1 also shares sentences with these, for which no sentence is quoted: head and neck tumor (4 papers); lymph node metastasis (3); autism spectrum disorder (2); clear cell renal cell carcinoma (2); ORAL Squamous Cell Carcinoma (2); astrocytoma (1); autoimmune disease (1); autoimmune thyroid disease (1); bipolar disorder (1); bladder urothelial carcinoma (1); brain tumor (1); cardiomyopathy (1); colon adenocarcinoma (1); colon cancer (1); colorectal tumor (1); depression (1); diabetes (1); endometrial cancer (1); hearing loss (1); liver cancer (1); lung (1); melanoma (1); multiple sclerosis (1); Nephropathy (1); pancreatic cancer (1); paraganglioma (1); pheochromocytoma (1); polymyositis (1); prostate adenocarcinoma (1); psoriasis (1).
A further 8 diseases each share a sentence with HOTAIRM1 in 1 paper.